HNF4A (hepatocyte nuclear factor 4 alpha)
Diseases named in the same sentence as HNF4A in open-access papers (continued):
Sharing a sentence is not in itself a finding about the gene and the disease.
cardiac hypertrophy (3 papers, 2024 to 2025). "In conclusion, the present study provides compelling evidence that the regulatory effect of Peli1 on HNF4α plays a crucial role in the impairment of FAO during pathological myocardial hypertrophy caused by pressure overload." (PMID 38346961, 2024). "Consistent with this, our study demonstrates that HNF4α overexpression enhances the transcription of FAO-related genes during pathological cardiac hypertrophy, resulting in increased FAO and improved myocardial hypertrophy." (PMID 40158182, 2025). "This study is the first to demonstrate that OTUD7B mitigates pathological cardiac hypertrophy by stabilizing HNF4α through deubiquitination." (PMID 40158182, 2025). "Our study aligns with these findings and confirms that increased expression of HNF4α promotes the transcription of FAO genes in pathological myocardial hypertrophy, leading to elevated FAO in cardiomyocytes and an improvement in myocardial hypertrophy." (PMID 38346961, 2024). "We confirmed that OTUD7B is involved in the regulation of ferroptosis in pressure overload-induced cardiac hypertrophy and highlighted that OTUD7B alleviates cardiac hypertrophy by regulating ferroptosis and fatty acid oxidation through deubiquitination and stabilization of HNF4α." (PMID 40158182, 2025). "We further used the antagonist BI6015 to inhibit HNF4α and delivered rAAV9-HNF4α to elevate myocardial HNF4α level, and confirmed that HNF4α inhibits the development of cardiac hypertrophy after TAC and is essential for the enhancement of FAO mediated by Peli1 knockout." (PMID 38346961, 2024). "Furthermore, we conducted experiments with myocardial-specific overexpression of HNF4α in mice using rAAV9-HNF4α, which demonstrated attenuated myocardial hypertrophy and improved cardiac function following TAC." (PMID 38346961, 2024). "Thus, Peli1 plays a crucial role in TAC-induced pathological myocardial hypertrophy by promoting the ubiquitinated degradation of HNF4α and affecting FAO (Graphical Abstract)." (PMID 38346961, 2024). "To validate whether the beneficial effect of Peli1 knockout on cardiac hypertrophy relies on HNF4α, we utilized the HNF4α antagonist BI6015." (PMID 38346961, 2024). "Therefore, we examined HNF4α expression in TAC-induced cardiac hypertrophy." (PMID 40158182, 2025). "Furthermore, it is crucial to evaluate whether HNF4α overexpression in the heart can rescue cardiac hypertrophy and normalize FAO genes in vivo." (PMID 38346961, 2024). "Therefore, we examined the expression of HNF4α in TAC-induced myocardial hypertrophy." (PMID 38346961, 2024). "In conclusion, this study provides robust evidence that OTUD7B-mediated deubiquitination of HNF4α is pivotal in reprogramming FAO and regulating ferroptosis during pressure overload-induced cardiac hypertrophy." (PMID 40158182, 2025). "In summary, our findings identify OTUD7B as a potential candidate for treating cardiac hypertrophy and highlight the promise of modulating FAO via an HNF4α-targeted strategy." (PMID 40158182, 2025). "In this study, we aimed to investigate the involvement of HNF4α and its ubiquitination, facilitated by Peli1, in FAO during pressure overload-induced cardiac hypertrophy." (PMID 38346961, 2024). "The introduction of rAAV9-HNF4α significantly increased the expression of HNF4α in the heart and attenuated TAC-induced cardiac hypertrophy." (PMID 38346961, 2024). "However, the role of HNF4α and its post-translational modifications in FAO during pathological myocardial hypertrophy remains unexplored." (PMID 38346961, 2024). "In this study, we provide evidence that the absence of Peli1 confers protection against pathological cardiac hypertrophy by suppressing the ubiquitination of HNF4α and enhancing the expression of FAO-related genes in the myocardium under pressure overload conditions." (PMID 38346961, 2024).
gastritis (3 papers, 2016 to 2021). Inflammation of the stomach. "Co-expression of HNF4α and IL-1R1 was a crucial indicator of malignant transformation from gastritis to GC, and was associated with a poorer prognosis in GC patients." (PMID 26870992, 2016). "To investigate the relevance of HDAC6 and HNF4α with gastric IM clinically, we examined the expression of both in normal, gastritis and IM tissues." (PMID 32705446, 2021). "Examination of clinical samples revealed that HNF4α and IL-1R1 levels increase with increasing severity of Hp-induced gastritis and reach their highest levels in GC." (PMID 26870992, 2016). "Our data indicate that HNF4α functions as an amplifier in infection-induced inflammation and as an oncogene even before the early GC stages, during the transformation from gastritis to GC." (PMID 26870992, 2016). "Overall, these data reveal that co-expression of HNF4α and IL-1R1 serves as a biomarker in transformation from gastritis to GC and their co-expression indicates worse prognosis of GC." (PMID 26870992, 2016). "To further confirm the relationship between TGR5 and metaplasia markers in IM, we detected TGR5, HNF4α, CDX2, and KLF4 expression using three consecutive slides of gastric tissue including 120 cases IM and 67 cases of chronic superficial gastritis by IHC." (PMID 32655894, 2020). "The H-scores of HNF4α, CDX2, and KLF4 protein were 33.0 ± 7.6 vs. 122.1 ± 8.3 (P < 0.01), 17.0 ± 5.6 vs. 60.4 ± 5.9 (P < 0.01), and 58.8 ± 7.3 vs. 129.7 ± 6.5 (P < 0.01) in gastritis vs. IM tissues, respectively." (PMID 32655894, 2020).
lipodystrophy (3 papers, 2017 to 2019). A congenital or acquired disorder characterized by abnormal loss or redistribution of the adipose tissue in the body. "In HNF4A, rs4812829 was most strongly weighted in the Beta Cell and Proinsulin clusters, whereas rs1800961 was most strongly weighted in the Lipodystrophy, Proinsulin, and Liver/Lipid clusters." (PMID 30240442, 2018). "In view of the pivotal role of HNF1α and HNF4α in the lipid metabolism and maintenance of serum cholesterol concentration in lipectomized rats, one may ask how these findings translate onto humans subjected to liposuction (or humans with lipodystrophy)." (PMID 30483910, 2019).
pancreatic adenocarcinoma (3 papers, 2019 to 2025). "Thus, HNF4α may serve as a prognostic marker for overall survival, and targeting HNF4α might reverse gemcitabine resistance and provide novel treatment strategies for pancreatic adenocarcinoma." (PMID 33462379, 2021). "However, the role of HNF4α in pancreatic adenocarcinoma (PDAC) has not been studied extensively and remains unclear." (PMID 30867652, 2019).
acute kidney injury (2 papers, 2020 to 2025). Sudden and sustained deterioration of the kidney function characterized by decreased glomerular filtration rate, increased serum creatinine or oliguria. "Similarly, HNF4A recruitment at enhancers and super-enhancers of key renal epithelial genes was reduced in the ischemia reperfusion model of acute kidney injury." (PMID 32998360, 2020).
alcoholic cirrhosis (2 papers, 2022 to 2023). "The increased methylation of HNF4A in viral and alcoholic cirrhosis could be related to the metabolic dysfunction in these diseases." (PMID 35655171, 2022).
Alzheimer disease (2 papers, 2021 to 2025). A progressive, neurodegenerative disease characterized by loss of function and death of nerve cells in several areas of the brain leading to loss of cognitive function such as memory and language. "According to a literature, HDAC2 overexpression contributes to the deacetylation of the hepatocyte nuclear factor 4α (HNF4A) transcription factor during Alzheimer's disease." (PMID 34586697, 2021).
bladder cancer (2 papers, 2021 to 2023). "An in vitro and in vivo study has shown that the knockdown of ALDH6A1 can promote cancer growth and reduce response to chemotherapy cisplatin through the negative regulation of the hepatocyte nuclear factor 4 alpha (HNF4α) in bladder cancer." (PMID 37476181, 2023). "Therefore, we intend to explore the related mechanism of the HNF4a gene's low-expression in BLCA further and hope to provide a clinical basis for the early diagnosis and prognosis of bladder cancer patients." (PMID 33628089, 2021).
brain tumors (2 papers, 2014). "HNF4A has also recently been shown to be expressed and regulated in meningioma brain tumours." (PMID 24728830, 2014).
chronic liver failure (2 papers, 2025). Liver failure that develops slowly and gradually for some time, possibly for years, often as the result of cirrhosis, or malnutrition. "C/EBPβ has a known function in liver regeneration after partial hepatectomy and recently we identified C/EBPβ as a key driver in acute-on-chronic liver failure, where it antagonizes HNF4α mediated transcription and drives the suppression of hepatocyte metabolic and synthetic function." (PMID 39969482, 2025).
clear cell carcinoma (2 papers, 2021 to 2023). "The clear cell carcinoma lesion was GATA3 negative and HNF4α positive; however, the urothelial cancer lesion was GATA3 positive and HNF4α negative." (PMID 34136304, 2021).
deafness (2 papers, 2018 to 2021). An inherited or acquired condition characterized by the complete loss of the ability to hear from one or both ears. "It expands the clinical phenotypes and supports speculation in the literature that HNF4A may be a candidate gene for deafness." (PMID 30005691, 2018). "According to their report, HNF4A may be a new candidate gene for deafness." (PMID 30005691, 2018).
Fanconi-Bickel syndrome (2 papers, 2020 to 2022). "Furthermore, specific mutations p.R63W and LRG_483t1:c.427-1G>A in HNF4α cause HI associated to hepatomegaly and renal Fanconi syndrome, a phenotype similar to Fanconi-Bickel syndrome (due to inactivating mutations of SLC2A2 resulting in nonfunctional glucose transporter 2, GLUT2)." (PMID 35422763, 2022). "Two genes, HNF4A (Hepatocyte Nuclear Factor 4 Alpha) and SLC2A2 (Solute Carrier Family 2 Member 2) causing renal Fanconi syndrome 4 and Fanconi-Bickel syndrome, respectively, are not yet classified due to the reduced number of cases published so far." (PMID 32150856, 2020). "This HNF4α mutations might decrease the expression of SLC2A2 in both liver and kidney, and are responsive to diazoxide therapy, unlike the Fanconi-Bickel syndrome." (PMID 35422763, 2022).
gallstones (2 papers, 2018 to 2023). Solid crystalline precipitates in the biliary tract, usually formed in the gallbladder, resulting in the condition of cholelithiasis. "Six of the novel gallstone associated variants, or highly correlated variants (r2 > 0.8), have been reported to associate with blood cholesterol levels (in HNF4A, HNF1A, FUT2, FADS2, MARCH8, and JMJD1C)." (PMID 30504769, 2018). "In our findings, however, among HIV-positive patients with gallstones, HNF4α was reduced in comparison to the levels in HIV-negative patients, yet CYP7A1 was upregulated." (PMID 36836631, 2023). "This demonstrates that HNF4α on its own is not a regulator of CYP7A1 in the pathogenesis of gallstones in HIV-positive patients." (PMID 36836631, 2023).
glioblastoma (2 papers, 2014 to 2016). The most malignant astrocytic tumor (WHO grade IV). "We discovered a novel glioblastoma control module centered on four major network hubs: Huntingtin, HNF4α, c-Myc and 14-3-3ζ." (PMID 25050814, 2014).
Hepatic cysts (2 papers, 2023). "Three probands carrying HNF4A missense mutation in this study showed variable pancreatic β-cell dysfunction, and the proband in family A had decreased HDL-C level and hepatic cyst as seen in image diagnostics (data not shown)." (PMID 37711893, 2023).
Hypoinsulinemia (2 papers, 2019 to 2025). A decreased concentration of insulin in the blood. "In mouse models, the targeted loss of Hnf4α in pancreatic β-cells was not sufficient to cause hypoinsulinemia and there are conflicting reports as to whether HNF4α is crucial in sustaining GSIS in these murine models." (PMID 30862908, 2019).
Impaired glucose tolerance (2 papers, 2020 to 2025). An abnormal resistance to glucose, i.e., a reduction in the ability to maintain glucose levels in the blood stream within normal limits following oral or intravenous administration of glucose. "In conclusion, the absence of HNF4α leads to impaired glucose tolerance and loss of insulin-producing beta cells, influenced by sex and age." (PMID 41017587, 2025). "In presence of family history of HY and/or Impaired Glucose Tolerance, Impaired Fasting Glucose or GDM, the hypothesis of ABCC8/KCNJ11, HNF1A or HNF4A gene mutations can be formulated." (PMID 32928245, 2020).
intestinal cancer (2 papers, 2016 to 2017). "On the other hand, HNF4α was reported to facilitate the initiation of intestinal cancer in the ApcMin mouse model." (PMID 26870992, 2016).
intrauterine growth restriction (2 papers, 2012 to 2018). "In humans, HNF4A methylation levels have been reported to differ in neonates with intrauterine growth restriction." (PMID 29598821, 2018). "The finding of increased HNF4A methylation in tissues from type 2 diabetic individuals is interesting considering the recent similar result in umbilical cord blood leukocytes from newborns with intrauterine growth restriction." (PMID 23251491, 2012).
kidney cancer (2 papers, 2015). Primary or metastatic malignant neoplasm involving the kidney. "For kidney cancer, the pattern was far more unanimous: several of the most enriched transcription factor target sites were targets of HNF4A." (PMID 25961905, 2015). "HNF4A is known to control cell proliferation in kidney cancer cell lines, and regulates a number of well-known cancer-associated genes to do so (e.g. CDKN1A and TGFA)." (PMID 25961905, 2015). "Interestingly, a recent study showed that NELL2 is a target gene for HNF4α, which is frequently lost in kidney cancer, and that expression of NELL2 contributes to HNF4α mediated inhibition of proliferation in kidney cells." (PMID 26624623, 2015).
medulloblastoma (2 papers, 2012 to 2023). A malignant, invasive embryonal neoplasm arising from the cerebellum. "We have also identified a potentially novel tumor suppressor in medulloblastomas based on the presence of HNF4A in D283MED exosomes." (PMID 22848702, 2012). "Surprisingly, drug treatment led to an increase in cell proliferation comparable to that of exosome treatment, suggesting that HNF4A may play a role as a tumor suppressor in this medulloblastoma cell line." (PMID 22848702, 2012).
neuroendocrine carcinoma (2 papers, 2024 to 2025). A malignant neuroendocrine neoplasm composed of cells containing secretory granules that stain positive for NSE and chromogranin. "Recent work identified a fifth neuroendocrine cancer subtype, defined by expression of HNF4A—a nuclear receptor that controls hepatic gene regulation." (PMID 39589879, 2024).
non-small cell lung carcinoma (2 papers, 2025). A group of at least three distinct histological types of lung cancer, including non-small cell squamous cell carcinoma, adenocarcinoma, and large cell carcinoma. "In non-small cell lung cancer, SE promote TGFβ-induced EMT by enhancing the expression of EMT-related transcription factors, while a BRD4-specific inhibitor JQ1 can inhibit SE-driven transcription of ETS2, HNF4A, JUNB, and other genes, resulting in the obstruction of EMT process." (PMID 39915455, 2025). "Finally, we examined whether HNF4α-positive grade 3 adenocarcinoma cell lines were present among the 39 non-squamous non-small cell lung cancer cell lines." (PMID 38710944, 2025).
ovarian carcinoma (2 papers, 2006 to 2021). A malignant neoplasm originating from the surface ovarian epithelium. "The specific role of TCF2 methylation in the development and progression of ovarian cancer remains unknown, but TCF2 mutations are known to affect expression of downstream genes such as HNF4α, PKHD1 and UMOD." (PMID 16479257, 2006).
renal fibrosis (2 papers, 2021 to 2023). A final common manifestation of a wide variety of chronic kidney diseases characterized by glomerulosclerosis and tubulointerstitial fibrosis. "Therefore, the decreased expression of Hnf4α after the early activation of fibroblasts in AKI may aggravate renal fibrosis by promoting EMT." (PMID 33777519, 2021). "Hnf4α, Pck1 and Timp-1 may play a pivotal role in the early activation of fibroblasts, providing novel therapeutic strategies for early prediction and treatment of renal fibrosis." (PMID 33777519, 2021). "At present, no direct evidence has confirmed whether Hnf4α can block renal fibrosis." (PMID 33777519, 2021).
ZIKV infection (2 papers, 2018 to 2020). "ZIKV infection of hPSC-HLCs and Huh7 cells was confirmed on 4d pi by immunofluorescence staining for ZIKV NS3 and the liver-enriched transcription factor HNF4α, demonstrating 6.4 ± 1.0% and 7.1 ± 2.0% ZIKV-infected hPSC-HLCs and Huh7 cells, respectively." (PMID 30566505, 2018).
Zinc deficiency (2 papers, 2010 to 2019). A deficiency of the essential metal Zinc; an essential cofactor for many enzymes. "The functional loss of HNF-4α by its small interfering ribonucleic acid (siRNA) has similar effect to zinc deficiency." (PMID 31174269, 2019). "Other experimental studies indicate that zinc deficiency decreased cell proliferation and related proteins such as hepatocyte growth factor (HGF), insulin like growth factor I (IGF), IGF binding protein 1 (IGFBP-1), MT, and cyclin D1, along with HNF-4α protein." (PMID 31174269, 2019).
ampullary cancer (1 paper, 2014). "For example, recent investigations have demonstrated that hepatocyte nuclear factor 4-alpha (HNF4α) is an effective tool for identifying different ampullary cancer subtypes and is an independent predictor of a favorable prognosis." (PMID 25104878, 2014).
anemia (1 paper, 2015). A reduction in the number of red blood cells, the amount of hemoglobin, and/or the volume of packed red blood cells. "Thus, augmentation of hepatic HNF4α signaling could be of value for the treatment of hypoferremia and anemia." (PMID 26527688, 2015).
Arthritis (1 paper, 2013). Inflammation of a joint. "Network analysis of the differentially expressed genes demonstrated that the steroid hormone receptor superfamily member hepatocyte nuclear factor 4 alpha (HNF4α) is a hub in several of the gene networks that distinguished children with arthritis from controls." (PMID 24000795, 2013).
atrial fibrillation (1 paper, 2025). A disorder characterized by an electrocardiographic finding of a supraventricular arrhythmia characterized by the replacement of consistent P waves by rapid oscillations or fibrillatory waves that vary in size, shape and timing and are accompanied by an irregular ventricular response. "Ultimately, we identified 17 plasma proteins with mediating effects, including Hepatocyte nuclear factor 4-alpha, which mediated the promotion of atrial fibrillation by serum urate, with mediation effect ratios ranging from 0.05% to 0.36%." (PMID 40469443, 2025). "Therefore, aberrant expression of HNF4a contributes to the onset of atrial fibrillation by exacerbating metabolic dysregulation, oxidative stress, and inflammatory responses." (PMID 40469443, 2025).
atrophic gastritis (1 paper, 2016). "HNF4α expression is increased in atrophic gastritis and, upon malignant transformation, reaches an even higher level." (PMID 26870992, 2016). "13C urea breath test was used to detect Hp infection in 30 patients with atrophic gastritis, and the level of HNF4α in Hp-positive patients was considerably higher than Hp-negative patients." (PMID 26870992, 2016). "Interestingly, IHC confirmed that expression of HNF4α already showed a higher expression level in atrophic gastritis mucosa than normal mucosa, along with a higher level of Ki-67 staining which nicely corroborated our previous finding that HNF4α contributed to gastric cell proliferation." (PMID 26870992, 2016).